NUP37 (nucleoporin 37)
Diseases named in the same sentence as NUP37 in open-access papers (continued):
Sharing a sentence is not in itself a finding about the gene and the disease.
glioma (continued). "Specifically, the G4 glioma exhibited the highest NUP37 expression, while the G2 glioma showed the lowest expression." (PMID 39174498, 2024). "Through extensive bioinformatics analysis and multi-omics sequencing, we ascertained that NUP37 overexpression in glioma led to an increase in various cell proliferation, division, and cell cycle-related signaling pathways." (PMID 39174498, 2024). "The results demonstrated that NUP37 was expressed more prominently in glioma tissues compared to normal brain tissues." (PMID 39174498, 2024). "In our prior cellular function experiments, we found that NUP37 depletion in glioma cells significantly curtailed cell proliferation and invasion, triggered apoptosis, induced nuclear migration, and led to various degrees of cell cycle arrest." (PMID 39174498, 2024). "After NUP37 depletion in glioma cells, disease-related enrichment analysis using the Disease Ontology and DisGeNET databases was performed on the DEGs." (PMID 39174498, 2024). "The findings from reduced representation bisulfite sequencing methylation sequencing showed a decrease in the methylation rate of CpG sites in glioma cells following NUP37 depletion." (PMID 39174498, 2024). "Collectively, these findings revealed the role of NUP37 in fostering the proliferation, invasion, and migration of glioma cells, primarily via its interaction with DNMT1." (PMID 39174498, 2024). "To investigate the expression of NUP37 at both the mRNA and protein levels, we obtained tumor tissue from 35 patients with gliomas and normal brain tissue from 15 patients who had experienced traumatic brain injury." (PMID 39174498, 2024). "Through in vitro and in vivo cellular functional experiments, we established that NUP37 depletion effectively hindered the proliferation, invasion, and other cellular activities of glioma cells." (PMID 39174498, 2024). "To delve deeper into the role of DNMT1 in these cellular functions, we overexpressed DNMT1 in NUP37-depleted glioma cells and assessed the changes in cell functions." (PMID 39174498, 2024). "Our findings indicated that the capabilities of invasion and migration were markedly influenced by NUP37 depletion in U87 and U251 glioma cell lines." (PMID 39174498, 2024). "To elucidate the expression relationship between NUP37 and other genes, we conducted a bioinformatics analysis of NUP37 in glioma using its co-expressed genes." (PMID 39174498, 2024). "Our study revealed that the expression level of NUP37 affects the proliferation and invasion of glioma cells, and that the overexpression of DNMT1 can alleviate the adverse effects caused by NUP37 depletion." (PMID 39174498, 2024). "In the present study, we performed cell cycle assays to examine the impact of NUP37 depletion on the cell cycle of U87 and U251 glioma cell lines." (PMID 39174498, 2024). "To explore the mechanism with this typical prognosis of NUP37, we conducted a GSEA study and believed that immunomodulatory pathways are ample in gliomas, which shows the important role of NUP37 in real TIME." (PMID 35093934, 2022). "This analysis suggested that NUP37 was extremely suppress immune infiltration, including iTregs, nTregs, and TAMs in glioma and pan-cancer." (PMID 35093934, 2022). "Using data from the cBioportal database, we described the gene variation of NUP37 in glioma and pan-cancer." (PMID 35093934, 2022). "Although there is so much evidence that NUP37 was a risk factor for the prognosis of glioma, we try to further explore the relationship between NUP37 and known biomarkers in glioma, which provide more evidence to support NUP37 as a malignant molecule." (PMID 34264013, 2021). "In the pathological process of glioma, some cancer‐related genes have been found and elaborated, but there are few reports about the relationship between NUP37 and the prognosis and clinical characteristics of glioma." (PMID 34264013, 2021).
glioma (continued). "Second, RT‐PCR technology was further used to detect the expression level of NUP37 in both clinical glioma samples and glioma cell lines." (PMID 34264013, 2021). "Collectively, our analysis gathered thousands of glioma samples and emphasized that the expression level of NUP37 increased in the pathological progression of glioma, which laid the foundation for our further analysis." (PMID 34264013, 2021). "All the data were based on the study of NUP37 mRNA level, so we further verified the change of NUP37 protein level in glioma." (PMID 34264013, 2021). "Second, IDH mutations and 1p19q codeletion are protective factors for the prognosis of glioma patients, but the expression of NUP37 is negatively correlated with them." (PMID 34264013, 2021). "To indirectly reveal how NUP37 was involved in the pathogenesis of gliomas, we divided the samples into high and low expression groups according to the expression of NUP37 and performed GSEA analysis." (PMID 34264013, 2021). "To examine the association of NUP37 with various clinicopathological features of glioma, we analyzed the expression levels of NUP37 in each clinical feature group using the Wilcoxon or Kruskal–Wallis test." (PMID 34264013, 2021). "The prognosis of the high expression group of NUP37 was apparently worse than the low expression group in grade III glioma." (PMID 34264013, 2021). "The results showed that there was a positive correlation between NUP37 and most known biomarkers of glioma such as ATRX, EGFR MGMT, CDK4, and so on." (PMID 34264013, 2021). "In particular, the expression level of NUP37 was positively correlated with the grade of glioma, which also supports that NUP37 is a malignant molecule." (PMID 34264013, 2021). "The main purpose of this study is to reveal the relationship between NUP37 and prognosis or clinical characteristics of glioma patients." (PMID 34264013, 2021). "The high expression of NUP37 in grade III of TCGA RNA‐seq had better diagnostic value for the 1‐year, 3‐year, and 5‐year survival of glioma patients (AUC >0.7)." (PMID 34264013, 2021). "Second, to evaluate the effect of NUP37 on the malignant biological behavior of glioma cells, siRNA was used to interfere with the expression of NUP37 in A172 cell." (PMID 34264013, 2021). "To clarify the relationship between NUP37 and patient prognosis in different grades of glioma, we divided the samples into grade II, III, and IV based on the clinical information, and a survival analysis was performed separately." (PMID 34264013, 2021). "Oncogenes are often closely related to the prognosis and clinical characteristics of patients with cancer, so we want to further reveal the relationship between NUP37 and the clinical and molecular characteristics of gliomas." (PMID 34264013, 2021). "In this study, we systematically explored the expression changes of NUP37 between gliomas and normal tissues through several dimensions of thousands of tissue samples." (PMID 34264013, 2021). "To deeply examine the role of NUP37 in the pathological process of glioma, we performed further investigations." (PMID 34264013, 2021). "The present study used a series of analytical methods and confirmed that the NUP37 expression level was elevated in gliomas and led to a poor prognosis of patients." (PMID 34264013, 2021). "NUP37 expression was slightly increased in gliomas of different grades compared to normal brain tissue." (PMID 34264013, 2021). "Encouragingly, compared with the high expression group of NUP37, the low expression group of NUP37 is closely related to the better prognosis of glioma patients." (PMID 34264013, 2021). "The results showed that NUP37 can activate a variety of carcinogenic signaling pathways, which have been reported in the pathological progress of glioma." (PMID 34264013, 2021). "Second, a series of bioinformatics analysis methods were used to analyze the NUP37 and glioma samples from multiple databases such as the CGGA, TCGA, GEO, HPA, and GEPIA." (PMID 34264013, 2021).
glioma (continued). "The expression of NUP37 was different in these two datasets, and the expression level in glioma specimens was higher than normal brain tissues." (PMID 34264013, 2021). "NUP37 for glioma patients (grades II) suggested a significant adverse effect on the prognosis of patient only in the CGGA RNA‐seq dataset, but no statistical significance was evident in the remaining two datasets." (PMID 34264013, 2021). "To reveal the role of NUP37 in the pathological process of glioma, we performed a multilevel analysis from glioma data derived from multiple database sources (CGGA RNA‐seq, CGGA microarray, and TCGA RNA‐seq)." (PMID 34264013, 2021). "This evidence suggested that DNMT1 might engage in cell proliferation-related pathways to preserve the biological function of certain glioma cells under the condition of NUP37 depletion." (PMID 39174498, 2024). "The endogenous expression of NUP37 in glioma cell lines was determined using a qPCR assay." (PMID 39174498, 2024). "Furthermore, the proliferation capability of glioma cells was higher in both DNMT1-overexpressing groups compared to the NUP37-depleted group." (PMID 39174498, 2024). "Kaplan–Meier survival analysis indicated that glioma patients with high NUP37 expression experienced significantly lower overall survival, disease-specific survival, and progression-free survival than those with low NUP37 expression." (PMID 39174498, 2024). "Notably, DNMT1 overexpression successfully mitigated the impaired proliferation, invasion, and migration of glioma cells instigated by NUP37 depletion." (PMID 39174498, 2024). "However, the precise relationship between NUP37 and DNMTs, as well as the mechanism that underpins their interaction in impacting glioma expression, remains largely elusive." (PMID 39174498, 2024). "Additionally, the apoptosis ratio of glioma cells in both DNMT1-overexpressing groups was observed to be higher than that in the NUP37-depleted group." (PMID 39174498, 2024). "However, the precise roles and significance of NUP37 in glioma are yet to be comprehensively explored." (PMID 39174498, 2024). "Moreover, the depletion of NUP37 in glioma cell lines led to a significant reduction in their metastatic capability." (PMID 39174498, 2024). "Moreover, we also revealed that NUP37 expression was a positively correlation between immune checkpoints, immunosuppressive genes, and immune regulation-related genes of glioma and pan-cancer." (PMID 35093934, 2022). "Finally, as above results were at the mRNA level, we further used immunohistochemistry to detect the protein expression of NUP37, and found that the protein expression level of NUP37 in glioma was also higher than that in the normal brain tissue." (PMID 34264013, 2021). "Silencing NUP37 suppresses malignant biological behaviors of glioma cells." (PMID 34264013, 2021). "Therefore, the present study examined the relationship between the expression of NUP37 and the clinical features of gliomas through the joint analysis of a large sample size in multiple databases." (PMID 34264013, 2021). "The protein expression level of NUP37 was obviously increased in glioma tissues." (PMID 34264013, 2021). "The theoretical basis of gene co‐expression infers the function of unknown genes through known gene dereplication, therefore, this part of the study will help to reveal NUP37 function in glioma." (PMID 34264013, 2021). "Therefore, we suggest that NUP37 is a valuable potential biomarker and molecular target for the diagnosis and treatment of glioma." (PMID 34264013, 2021). "The expression level of NUP37 was obviously increased in both glioma cell lines and glioma tissues." (PMID 34264013, 2021). "The expression level of NUP37 was positively correlated with the age of glioma patients." (PMID 34264013, 2021). "Finally, we verified the effect of NUP37 on the behavior of glioma cell line by traditional experimental methods." (PMID 34264013, 2021).
glioma (continued). "However, in order to demonstrate the role of NUP37 in glioma more scientifically and rigorously, it is necessary to use traditional experimental methods to verify the analysis results." (PMID 34264013, 2021). "First, we validated the protein expression levels of NUP37 in glioma using HPA database." (PMID 34264013, 2021). "Finally, knockdown of NUP37 showed that the proliferation and migration ability of A172 glioma cell line were significantly decreased and previous articles also support the view that NUP37 is an oncogene." (PMID 34264013, 2021). "However, in glioblastoma, only the CGGA database showed that the high expression of NUP37 leads to the decrease of the overall survival time of glioma patients." (PMID 34264013, 2021). "Finally, the meta‐analysis of thousands of tissue samples from seven datasets and cell proliferation and migration experiments confirmed that NUP37 has a malignant effect on glioma." (PMID 34264013, 2021). "Consequently, in order to make up for these deficiencies, we used the traditional experimental methods to verify the carcinogenic effect of NUP37 in glioma." (PMID 34264013, 2021). "First, we used RT‐qPCR to examine the expression levels of NUP37 in glioma cell lines and tissues." (PMID 34264013, 2021). "NUP37 is highly expressed in glioma patient tissues and glioma cells, significantly correlates with reduced overall survival, and may serve as an independent prognostic factor with some diagnostic value." (PMID 34264013, 2021). "Moreover, we illustrated that DNMT1 overexpression, in the context of NUP37 depletion, could partially restore both the proliferation and invasion of glioma cells." (PMID 39174498, 2024). "However, the immunomodulatory function and biomarker role of NUP37 in glioma and pan-cancer remain unclear." (PMID 35093934, 2022). "However, the immunomodulatory function and biomarker role of NUP37 in glioma and pan-cancer remains unclear." (PMID 35093934, 2022). "Finally, immunohistochemistry was also done to analyze the expression levels of NUP37 protein in normal brain tissue, low‐grade glioma, and high‐grade glioma using collected clinical samples (4 normal brain samples, 7 low‐grade glioma samples, and 19 high‐grade glioma samples)." (PMID 34264013, 2021). "In addition, as the expression of NUP37 was highly positively correlated with the genes encoding PD‐L1 (CD274) and PD‐L2 (PDCD1LG2), it is more importantly that PD‐L1 and PD‐L2 are an immune checkpoint inhibitor in gliomas." (PMID 34264013, 2021). "Therefore, in order to make up for the difference between the 3 databases, we collected 23 cases of glioblastoma to drew the survival curve, and found that the high expression of NUP37 in glioblastoma had only weak statistical significance on the prognosis of gliomas." (PMID 34264013, 2021). "Finally, we next compare the relationship between NUP37 and known biomarkers in gliomas." (PMID 34264013, 2021). "This study demonstrates for the first time a malignant role of NUP37 in glioma and provides a vision to unravel the complex pathological mechanisms of glioma and a potentially valuable biomarker for implementing individualized diagnosis and treatment of glioma." (PMID 34264013, 2021). "To summarize, in glioma cells with NUP37 depletion (NC + KD), overexpression of DNMT1 (KD + OE) partially restored the proliferation, invasion, and migration of glioma, while it decreased apoptosis to varying degrees." (PMID 39174498, 2024). "In conclusion, our study underscored the significance of NUP37 and DNMT1 in the regulation of glioma proliferation." (PMID 39174498, 2024). "Integrating these findings with previous sequencing data and cellular functional assays, we proposed that NUP37 depletion induced DNMT1 downregulation, thus inhibiting glioma cell proliferation and invasion." (PMID 39174498, 2024). "In the present study, we conducted an in-depth examination of the expression levels of NUP37 and DNMT1 in gliomas." (PMID 39174498, 2024).
glioma (continued). "Third, in the Chinese Glioma Genome Atlas (CGGA) database, we found that NUP37 expression was higher in later tumor stages of glioma." (PMID 35093934, 2022). "The CCK-8 cell proliferation assay revealed that the proliferation activity of the glioma cells reached its peak in the double-negative control group, while it was at its lowest in the group when NUP37 was depleted." (PMID 39174498, 2024). "In the apoptosis experiment, the apoptosis ratio of the glioma cells was found to be the lowest in the double-negative control group and the highest in the NUP37-depleted group." (PMID 39174498, 2024). "We noted overexpression of NUP37 and DNMT1 in glioma tissues." (PMID 39174498, 2024). "Moreover, clinical correlation analysis revealed a positive correlation between NUP37 expression levels and the World Health Organization (WHO) grade of glioma." (PMID 39174498, 2024). "The levels of invasion and migration of glioma cells peaked in the double-negative control group, reached their lowest in the NUP37-depleted group, and were elevated in both DNMT1-overexpressing groups when compared to the NUP37-depleted group." (PMID 39174498, 2024). "The carcinogenic effect of NUP37 has been reported recently in a variety of tumors, but its research in the field of glioma has not been paid attention." (PMID 34264013, 2021). "Previous studies have shown that the expression level of NUP37 as an oncogene was significantly increased in tumor tissues, but it is not known in glioma." (PMID 34264013, 2021). "Similarly, overexpression of NUP37 activates PI3K/AKT signaling, promoting the proliferation, migration, and invasion of gastric cancer (GC) cells, and forms an immunosuppressive microenvironment in gliomas." (PMID 39080077, 2024). "Furthermore, continued investigations into the interaction between NUP37 and DNMT1, as well as their specific signaling pathways and molecular mechanisms, will enhance our understanding of glioma pathogenesis and broaden the therapeutic arsenal for this devastating disease." (PMID 39174498, 2024). "However, NUP37 as oncogene was not reported in gliomas, especially its relationship with clinical features." (PMID 34264013, 2021). "However, the relationship between the significantly high expression of NUP37 and the prognosis of glioma patients is not clear." (PMID 34264013, 2021). "We retrieved multiple well‐known databases and found no reports about NUP37 in glioma, so we could only collect the extant data in the database to complete the meta‐analysis to further confirm the effect of NUP37 on the prognosis of glioma patients." (PMID 34264013, 2021). "Similarly, the OrisTM Wound Healing Assay findings revealed that the migration level of glioma cells was greatest in the double-negative control group, least in the NUP37-depleted group, and higher in both DNMT1-overexpressing groups compared to the NUP37-depleted group." (PMID 39174498, 2024).
non-small cell lung carcinoma (3 papers, 2022 to 2024). A group of at least three distinct histological types of lung cancer, including non-small cell squamous cell carcinoma, adenocarcinoma, and large cell carcinoma. "In non-small cell lung cancer, NUP107 overexpression has also been previously reported, and another nucleoporin family member, NUP37, was found responsible for increased cell proliferation in vitro." (PMID 37345045, 2023). "Nup37 has a positive role in the progression of HCC and other cancers as well, while its silencing induces inhibition of cell proliferation, G1 phase cell cycle arrest, and apoptosis in non-small cell lung cancer cells." (PMID 36016316, 2022).
colon cancer (2 papers, 2022 to 2023). "The transcript levels of four NUPs (NUP210, NUP58, NUP37, and Rae1) were higher in colon cancer tissue among BRD4-bound NUPs." (PMID 35159127, 2022).
gastric cancer (2 papers, 2024). A primary or metastatic malignant neoplasm involving the stomach. "Moreover, NUP37 facilitates the PI3K/AKT/mTOR pathway to accelerate tumorigenesis in gastric cancer." (PMID 38955795, 2024).